ATG7 (autophagy related 7)
Diseases named in the same sentence as ATG7 in open-access papers (continued):
Sharing a sentence is not in itself a finding about the gene and the disease.
colorectal tumor (2 papers, 2018). "In general, F. nucleatum promotes CRC chemoresistance by activating autophagosome formation and subsequently inducing autophagy-related proteins, such as pULK1, ULK1, and ATG7, in colorectal tumor cells." (PMID 30065719, 2018).
coronary artery disease (2 papers, 2022 to 2024). "Logistic regression analysis (binary model) in all subjects when coronary artery disease was used as a response variable and age, gender, BMI, arginase-1, nitrate, nitrite, and the 2 single-nucleotide polymorphisms of ATG7 were taken as independent variables." (PMID 35777002, 2022). "Relationship of ATG7 rs1375206 C/G and rs550744886 C/G polymorphism with clinical parameters in coronary artery disease patients." (PMID 35777002, 2022).
Crohn disease (2 papers, 2012 to 2025). A gastrointestinal disorder characterized by chronic inflammation involving all layers of the intestinal wall, noncaseating granulomas affecting the intestinal wall and regional lymph nodes, and transmural fibrosis. "ATG7 level was markedly elevated in inflamed mucosa tissues and peripheral blood CD4+ T cells of patients with active Crohn's disease compared to healthy individuals." (PMID 40887825, 2025). "Interestingly, we could not detect inflammatory alterations in unchallenged Atg7IEC-KO mice suggesting that Atg7 deficiency in the intestinal epithelium is not sufficient to induce a Crohn's disease like phenotype." (PMID 22291845, 2012).
diabetic cardiomyopathy (2 papers, 2021 to 2022). Diabetic cardiomyopathy is a disorder of the heart muscle in people with diabetes. "Autophagy related 7 (Atg7)-and Parkin-dependent mitophagy plays an essential role in the maintenance of mitochondrial function and protects the heart during the early development of diabetic cardiomyopathy." (PMID 35783853, 2022).
disc degeneration (2 papers, 2023 to 2024). "Melatonin enhances Atg7 transcription and translation by inhibiting miR-106a-5p in annulus fibrosus cells in disc degeneration patients." (PMID 38553562, 2024). "It was also found that NRF1 induces autophagy and inhibits apoptotic responses by promoting Atg7 expression in compressed NP cells, delaying disc degeneration." (PMID 37915003, 2023). "A significant increase in miR-654-5p and its inhibition of Atg7 were observed in degenerated nucleus pulposus tissues from intervertebral disc degeneration (IDD) patients." (PMID 38553562, 2024).
endometrial cancer (2 papers, 2021 to 2025). Primary or metastatic malignant neoplasm involving the endometrium (mucous membrane that lines the endometrial cavity). "In endometrial cancer, somatic mutations were found in several autophagy genes, including mTOR/ERDj and ATG7." (PMID 41233892, 2025).
endometriosis (2 papers, 2016 to 2022). The growth of functional endometrial tissue in anatomic sites outside the uterine body. "Notably, neutrophil degranulation genes have been reported to be associated with endometriosis, such as A1BG (a diagnostic marker for stage II, III and IV endometriosis) and ATG7 (an autophagy gene in ovarian endometriosis)." (PMID 35401535, 2022).
erythroleukemia (2 papers, 2016 to 2021). Acute erythroid leukemia characterised by the presence of at least 50% erythroid precursors and at least 20% myeloblasts in the bone marrow. "Starvation-induced alternative autophagy was confirmed in Atg5−/− MEFs and Atg7−/− erythroleukemia K562 cells." (PMID 34831462, 2021). "Using CRISPR/Cas9 deletion of the canonical autophagy-essential gene Atg7, we found that erythroleukemia K562 cells are armed with two sets of autophagic machinery." (PMID 27091640, 2016). "The same mitophagy pathway was found to participate in the reprogramming process of iPSCs; in contrast, Atg7-independent mitophagy regulated ROS levels and DNA damage repair (via regulation of RAD50) and suppressed apoptosis in erythroleukemia cells exposed to radiation or CCCP." (PMID 34831462, 2021).
fibrosarcoma (2 papers, 2016 to 2020). A malignant mesenchymal fibroblastic neoplasm affecting the soft tissue and bone. "Knockdown of autophagy related genes ATG7 or Beclin1 enhanced necrotic cell death in fibrosarcoma cells, indicating that autophagy protects against necrotic cell death." (PMID 27283985, 2016).
Gait ataxia (2 papers, 2022 to 2024). A type of ataxia characterized by the impairment of the ability to coordinate the movements required for normal walking. "Clinical phenotypes associated with congenital deficiencies in autophagy genes ATG7, ATG5 and SQSTM 1 further support the selective vulnerability of PCs, particularly in gait ataxias." (PMID 39367235, 2024). "Unexpectedly, Wap-Cre driven Atg7-CKO mice showed progressive motor deficits, manifesting primarily as gait ataxia suggestive of cerebellar involvement." (PMID 35404932, 2022).
gestational diabetes (2 papers, 2020 to 2024). Carbohydrate intolerance first diagnosed during pregnancy. "Another study aimed at finding epigenetic alternations in miRNAs and DNA through an in silico approach identified Atg7 as a hub gene and a potential target for gestational diabetes mellitus (GDM) diagnosis and treatment." (PMID 38553562, 2024). "Moreover, from these genes, ATG7, DICER1, IGF1R and RANBP2 may play an important role in the genesis and growth of gestational diabetes mellitus and might serve as aberrantly methylation‐based or expression of miRNA‐targeting biomarkers for precise diagnosis and treatment of GDM in the future." (PMID 33085184, 2020).
Globozoospermia (2 papers, 2016 to 2021). Any structural anomaly of the acrosome resulting in a round sperm head. "The role of autophagy flux in globozoospermia wasstudied by the western blot analysis to detect ATG7 andLC3II/LC3 proteins." (PMID 33650822, 2021). "Specific knockout of Atg7 in mouse germ cells resulted in irregular or nearly round-headed spermatozoa, which is similar to human globozoospermia, thus the knockout mice were infertile because of the defection of acrosome biogenesis." (PMID 27098880, 2016). "The increased expression of ATG7 and unaltered expression of LC3II/LC3 may indicate that theautophagy pathway is initiated but not completely executed in spermatozoa of individuals with globozoospermia." (PMID 33650822, 2021).
gout (2 papers, 2023 to 2025). A condition characterized by painful swelling of the joints, which is caused by deposition of urate crystals. "Next, we explored the function of the circ_0058051/miR-129-5p/ATG7 axis by simulating inflammatory gout recurrence in vitro." (PMID 41221017, 2025). "In the 20 paired cases, compared with stable gout cases, the expression of circ_0058051 and ATG7 was significantly greater during a gout attack and even greater in patients with gout recurrence." (PMID 41221017, 2025). "This study is the first to confirm that circ-0058051 promotes ATG7 expression by inhibiting miR-129-5p, which promotes gout recurrence." (PMID 41221017, 2025). "In this study, we examined the expression of circ_0058051, miR-129-5p, and ATG7 in peripheral blood mononuclear cells from gout patients at three different stages of inflammation, that is, the first attack, stabilization, and inflammatory recurrence." (PMID 41221017, 2025). "The expression levels of circ_0058051 and ATG7 were significantly greater in the GA group than in the HC group, and the expression of miR-129-5p was significantly lower in the gout group than in the HC group." (PMID 41221017, 2025). "The gout group expressed significantly more circ_0058051 and ATG7 and significantly less miR-129-5p than the HC group." (PMID 41221017, 2025). "The results of our study suggest that ATG7 is a key downstream factor in the inflammatory response inhibited by miR-129-5p in gout recurrence." (PMID 41221017, 2025). "We found that among the three, circ_0058051 and ATG7 expression were highest and miR-129-5p expression was lowest in the PBMCs of patients with gout-related inflammation recurrence." (PMID 41221017, 2025). "Previous studies by our group revealed abnormal circ_0058051, miR-129-5p, and ATG7 expression in patients with gout." (PMID 41221017, 2025). "To clarify the role of ATG7 in the progression of gout, we transfected THP-1 macrophages with an ATG7 overexpression plasmid and verified the transfection efficiency." (PMID 41221017, 2025). "The circ_0058051/miR-129-5p/ATG7 axis is expected to be a new target for the prevention of gout recurrence." (PMID 41221017, 2025). "In addition, we observed that ATG7 was negatively regulated by miR-129-5p, which inhibited the inflammatory response and autophagy in gout by inhibiting the expression of ATG7." (PMID 41221017, 2025). "In this study, we found that ATG7 levels were significantly increased in gout patients." (PMID 41221017, 2025). "Furthermore, the expression of ATG7 was significantly increased during the recurrence period in in PMBCs collected from gout patients compared to PMBCs collected after the first attack or the stabilization of treatment." (PMID 41221017, 2025). "Notably, the expression levels of circ_0058051 and ATG7 were significantly greater and the expression level of miR-129-5p was significantly lower in patients with recurrent gout than in the 20 patients with a first gout attack." (PMID 41221017, 2025). "We hypothesized that circ_0058051, miR-129-5p, and ATG7 are involved in the molecular mechanism of gout inflammation recurrence." (PMID 41221017, 2025). "The protein concentrations of inflammatory cytokines (IL-1β, TNF-α, and IL-6) significantly increased after ATG7 overexpression in MSU-stimulated THP-1 macrophages, suggesting that ATG7 may be involved in the mechanism of gout recurrence by promoting the release of inflammatory cytokines." (PMID 41221017, 2025). "To this end, we treated the peripheral blood of patients with intercritical gout with MSU crystals and either overexpressed or knocked down circ_0058051, miR-129-5p, and ATG7 in THP-1 macrophages." (PMID 41221017, 2025).
gout (continued). "This study will help to further elucidate the correlation between ATG7 and PAD4, to provide a novel strategy to improve the therapeutic efficacy of gouty arthritis." (PMID 37810893, 2023). "In the simulation model of gout recurrence in the peripheral blood of intercritical gout patients stimulated with MSU, circ_0058051 peaked 2 h after MSU stimulation, ATG7 peaked 1 h after MSU stimulation, and miR-129-5p expression was lowest 1 h after MSU stimulation." (PMID 41221017, 2025). "ATG7 may induce excessive autophagy and activate NLRP3 to release inflammatory cytokines during gout recurrence." (PMID 41221017, 2025).
Hepatitis (2 papers, 2018 to 2024). Inflammation of the liver. "The mRNA and protein levels of Atg7 were both decreased in ARC pretreatment group, thus indicating that ARC might protect liver from ConA-induced hepatitis through the inhibition of the upregulation of Atg7." (PMID 30177931, 2018).
herpesvirus infection (2 papers, 2015 to 2024). "In addition to these functions, bone marrow-derived dendritic cells from Vav-Atg7−/− mice mitigated the response to α-herpesvirus infection and viral DNA recognition due to reduction of ATG7-dependent IFN-β expression." (PMID 26404030, 2015). "Additionally, myeloid-specific knockout of several autophagy genes (RB1CC1, Beclin1, ATG3, ATG5, ATG7, ATG14, or ATG16L) in animals subjected to herpesvirus infection results in elevated inflammation and prevented viral reactivation from latency." (PMID 38447109, 2024).
inflammatory bowel disease (2 papers, 2025). A spectrum of small and large bowel inflammatory diseases of unknown etiology. "Nevertheless, the specific contribution of Atg7 in CD4+ T cells sensitive immune responses in inflammatory bowel disease (IBD) remains largely unclear." (PMID 40887825, 2025).
injury (2 papers, 2019 to 2024). Damage inflicted on the body as the direct or indirect result of an external force, with or without disruption of structural continuity. "Autophagic cell death has been shown to play a critical role in the process of perinatal brain injury, and in this study we found that different alleles and genotypes of the ATG7 gene SNPs and higher levels of circulating ATG7 protein were significantly associated with CP." (PMID 31749688, 2019). "In this study, we found that the HuR protein expression was inducible in the mouse model of APAP‐induced liver injury and found that HuR could protect against APAP‐induced liver injury by promoting the expression of NRF2, cyclin A1, cyclin B1, cyclin D1, CDK2, ATG3, ATG5 and ATG7." (PMID 39614424, 2024).
intestinal tumors (2 papers, 2015 to 2017). "Nonetheless, thus far, no overt evidence has been obtained from Villi-Atg7−/− mice that Atg7 is implicated in the pathogenesis of intestinal tumors and maintenance of gut immune homeostasis." (PMID 26404030, 2015).
laryngeal carcinoma (2 papers, 2023 to 2025). Carcinoma that arises from the laryngeal epithelium. "Starved laryngeal cancer cells show a significant mRNA increase in autophagy‐related markers such as ATG7, ATG16L, Beclin1 and LC3b at different time points, with a corresponding decrease in p62 levels, indicating the occurrence of autophagy." (PMID 39893643, 2025). "In our preliminary study, we found low representation of ATG7 expression in laryngeal carcinomas (22.2%)." (PMID 37173926, 2023). "Similar observations are made in cell lines: compared to normal laryngeal cells, autophagy‐related markers such as ATG7, ATG16L, Beclin1 and LC3b protein expression levels are elevated in laryngeal cancer cells, while p62 expression levels decrease." (PMID 39893643, 2025). "The data analysis of the TCGA‐HNSC reveals a positive correlation between the expression of CTSL and autophagy‐related markers such as ATG5, ATG7, ATG12, ATG16L and LC3b, suggesting a connection between CTSL and autophagy in laryngeal cancer." (PMID 39893643, 2025).
Legionella Infection (2 papers, 2019 to 2024). "One study reported that Atg7 gene methylation can be affected by Legionella Infection, which causes a reduction in Atg7 mRNA57." (PMID 38553562, 2024). "Legionella Infection can irreversibly change the GATC motif to G(6 mA)TC in the Atg7 promoter region, causing a time-dependent reduction in Atg7 mRNA, which further inhibits autophagosome formation." (PMID 38553562, 2024). "Interestingly, in comparison with inactive Legionella, Legionella infection showed a significant reduction of both Atg7 and LC3B mRNA in a time-dependent manner following infection." (PMID 32064256, 2019).
lentivirus infection (2 papers, 2018 to 2020). Virus diseases caused by the Lentivirus genus. "The knockdown efficiency was verified by western blots, and the results showed that both ATG5 and ATG7 were significantly reduced after shATG5-1 and shATG7 lentivirus infection, while the knockdown efficiency of shATG5-2 was not satisfied." (PMID 29416002, 2018).
lung fibrosis (2 papers, 2021 to 2022). "Comparing with the wild type mice, more serious fibrotic lesions occur in the EC-ATG7-/- mice, indicating that progressive lung fibrosis may be accompanied by the loss of ATG7." (PMID 35111363, 2022). "Loss of autophagy gene ATG7 in endothelial cells induces EndMT and activates the TGF-β signaling pathway, aggravating pulmonary fibrosis." (PMID 35111363, 2022). "Fibroblast-specific knockout of Atg7 reduced the TβRIact-induced increase in Ashcroft scores and in fibrotic area as well as myofibroblast counts and hydroxyproline content compared to mice with normal expression of Atg7 in experimental pulmonary fibrosis." (PMID 34285225, 2021).
malnutrition (2 papers, 2021 to 2023). Inadequate nutrition resulting from poor diet, malabsorption, or abnormal nutrient distribution. "ATG3, ATG5, ATG7, or ATG16L1 deficiency in mice leads to malnutrition and energy expenditure, leading to death shortly after birth." (PMID 33854691, 2021).
metastatic cancer (2 papers, 2016 to 2025). A carcinoma which has spread from the original site of growth to another anatomic site. "Our findings revealed that the expression levels of Beclin-1, LC3B, and ATG7 proteins in epithelial cells progressively increased from adjacent normal tissues to primary tumors, and were further elevated in metastatic cancers (all P < 0.001)." (PMID 39922805, 2025).
myeloid leukemia (2 papers, 2021 to 2023). A clonal proliferation of myeloid cells and their precursors in the bone marrow, peripheral blood, and spleen. "In contrast, treatment with HDACi in Down syndrome-associated myeloid leukemia repressed autophagy, probably due to the downregulation of ATG7 gene, was associated with its hyperacetylation." (PMID 34944907, 2021). "An analysis of Down syndrome-associated myeloid leukemia cell lines showed that HDAC inhibitors suppress autophagy by increasing the acetylation of autophagy-related proteins such as ATG7 and exhibit autotoxic activity against cells with low autophagic activity." (PMID 38069042, 2023). "Specifically, mono treatment with valproic acid, SAHA, TSA, panobinostat or JQ2, a specific HDAC1/2 inhibitor, increased acetylation levels of ATG7, promoted a decrease in autophagic flux, and induced apoptosis in myeloid leukemia cells." (PMID 34944907, 2021).
periodontitis (2 papers, 2021 to 2023). An acute or chronic inflammatory process that affects the tissues that surround and support the teeth. "Our previous clinical study of periodontitis patients demonstrated decreased expression levels of the autophagy-related proteins ATG5-12 conjugates, ATG16L1 and ATG7, at the protein and mRNA levels." (PMID 37764988, 2023). "Interestingly, Vit D supplementation rescued autophagy in periodontitis patients, and increased the expression of Beclin1, ATG5-12 conjugate, ATG16L1 and ATG7." (PMID 37764988, 2023).
poliovirus infection (2 papers, 2021). An disease or disorder caused by infection with Enterovirus C. "Atg7-dependent activation of autophagy in neuronal cells in response to poliovirus infection was associated with reduced virus production and better infection control in human patients." (PMID 34452452, 2021). "ATG7 also limits poliovirus infection; A defect in stimulus‐induced autophagy was observed in primary fibroblasts taken from a patient with poliomyelitis after polio infection, with exome sequencing identifying a heterozygous p.A388T (NP_006386.1) ATG7 variant." (PMID 34725936, 2021).
pulmonary arterial hypertension (2 papers, 2019 to 2023). Pulmonary arterial hypertension (PAH) is a group of diseases characterized by mean pulmonary artery pressure >20 mmHg and elevated pulmonary arterial resistance leading to right heart failure. "Meanwhile, Glucagon-like peptide 1 receptor agonists attenuate autophagy via Drp1/NOX- and Atg-5/Atg-7/Beclin-1/LC3β pathways to improve pulmonary hypertension." (PMID 37491292, 2023).
rheumatoid arthritis (2 papers, 2016 to 2022). A chronic, systemic autoimmune disorder characterized by inflammation in the synovial membranes and articular surfaces. "Autophagy was activated in the osteoclasts of human rheumatoid arthritis by upregulating ATG7, and ATG7 overexpression decreased osteoclastogenesis and TNFα-induced bone erosion." (PMID 36358952, 2022).